MMP9 (matrix metallopeptidase 9)
Diseases named in the same sentence as MMP9 in open-access papers (continued):
Sharing a sentence is not in itself a finding about the gene and the disease.
depression (continued). "No group differences between major depressive disorders and controls were found for MMP-9 in platelets." (PMID 35370878, 2022). "It is to be noted that the literature on MMP-9 is more established for bipolar disorder rather than depression." (PMID 35370878, 2022). "Moreover, a significant positive correlation was observed between Hamilton Rating Scale for Depression (HAMD) scores and MMP-9 level in the serum." (PMID 35370878, 2022). "Combined with our experimental results, the FTO in ACC of NP mice reduces the protein expression of MMP-9 by affecting the translation efficiency of MMP-9 mRNA, thus hindering the transformation from proBDNF to mBDNF and resulting in anxiety- and depression-like behaviors in mice." (PMID 35634463, 2022). "Interestingly, transcript and protein levels of MMP-2, MMP-9 and TIMP-2 were found to be downregulated in patients with the recurrent depressive disorder as compared to healthy individuals." (PMID 31172215, 2019). "Moreover, reduced mRNA and protein levels of MMP-2, MMP-9 and TIMP-2 were observed in patients diagnosed with depression and displaying lower performance in cognitive tasks, as compared to healthy subjects." (PMID 31172215, 2019). "While clinical studies documenting the role of MMP-9 in the emergence of stress-induced depression are lacking, preclinical studies have demonstrated that exposure to social defeat results in elevations of the cytokine IL-1α and MMP-9." (PMID 30416436, 2018). "(1<RR<2,56).RA=0,31]; 88,2% of the patients with positive MMP–9 have related episodes of depression in pre–operatory stage versus 56.2% of those without extracellular disk matrix modifications." (PMID 22567050, 2011). "The risk of not improving their state of unease or depression after 3 months of the surgery on those with positive MMP–9, is statistically significant, higher than those with negative MMP–9 results (X2=5,16, RA=0,26)." (PMID 22567050, 2011). "However, the regulation of MMP-9 levels does not appear to be the sole factor driving the modulation of anxiety and depression-like manifestations." (PMID 40405318, 2025). "Some studies also reported no obvious correlation between MMP-9 level and depression." (PMID 35370878, 2022). "In an animal model of prolonged stress (restrain of a mouse for 6 h per day, repeated for 21 days) that may contribute to depression, proteolytic activity of MMP-9 was shown to be enhanced in CA1 but not in CA3 of the hippocampus." (PMID 31172215, 2019). "Interestingly, we found a positive correlation between serum MMP-9 levels and the severity of depression in patients with MDD, although the role of MMP-9 in the pathophysiology of MDD is currently unknown." (PMID 22880079, 2012). "Clinically, we observed that the modification of the extracellular disk matrix has a negative impact on the improvement of the post–surgery psychical state, only 73,5 of those with positive MMP–9 have declared the lack of pre–operatory depression, in comparison with the 100% MMP–9 negative subjects." (PMID 22567050, 2011). "However, the specific effects of SED and related psychiatric disorders, including ADHD, bipolar disorder (BD), and major depressive disorder (MDD), on matrix metalloproteinase-9 (MMP-9), proinflammatory cytokine levels, and inhibitory control function remain unclear." (PMID 40219625, 2025). "The secondary aim was to investigate whether MMP-9 levels correlate with severity of schizophrenic (assessed with the Positive and Negative Syndrome Scale (PANSS)) and depressive (assessed with the Calgary Depression Scale for Schizophrenia (CDSS)) symptoms and clinical improvement during our study." (PMID 27409603, 2016). "In patients with schizophrenia, individual expression levels of MMP-9 were not statistically significant, except for the MMP-9/TIP-1 ratio, while high levels of MMP-9 are crucial for the pathogenesis of depression, ASD, and FXS." (PMID 38254696, 2024).
preeclampsia (59 papers, 2008 to 2026). Preeclampsia is a hypertensive disorder of pregnancy that is characterized by new-onset hypertension with proteinuria presenting after 20 weeks of gestation, and depending on mild or severe forms may initially present with severe headache, visual disturbances, and hyperreflexia. "Dysregulation of MMP‐2 and/or MMP‐9 has been implicated in both gestational hypertension and preeclampsia." (PMID 40844502, 2025). "In a study looking at the association of MMP-9 in severe preeclampsia, mild preeclampsia, and normal pregnancies; MMP-9 expression was reduced in severely preeclamptic patients, but was not different between mild preeclampsia and normal pregnancies." (PMID 37089425, 2023). "Decreasing MMP2 and MMP9 impairs spiral artery remodeling and causes initial pathological symptom of preeclampsia during early gestation." (PMID 36910123, 2022). "Dysregulation of MMP-2 and MMP-9 has been implicated in abnormal vasodilation, placentation, and uterine expansion in preeclampsia." (PMID 33803206, 2021). "Mmp2 and Mmp9 are the most abundant gelatinases expressed during trophoblast invasion in humans, and reduced expression of Mmp9 is associated with preeclampsia in mice and humans." (PMID 34767447, 2021). "A major conclusion of this study was that higher levels of MMP-2 and MMP-13 and lower levels of MMP-9 are possibly associated with both early- and late-onset severe preeclampsia." (PMID 33803206, 2021). "Meanwhile, LGA was associated with maternal plasma VEGF (p<0.05, +ve) and MMP-9 (p<0.05, -ve) and gestational hypertension (p<0.01, +ve), pre-pregnancy body mass index (p<0.01, +ve), parity (p<0.05, +ve) and education (p<0.05, -ve)." (PMID 30383759, 2018). "An early report regarding MMP-9-1562 C/T polymorphism showed that women carrying the T allele were less likely to develop preeclampsia." (PMID 28726716, 2017). "We compared the distribution of genotypes for NOS3 G894T, T-786C, and VNTR in intron 4, as well as MMP2 C-1306T and MMP9 C-1562T, and tested their association with preeclampsia and its major complications." (PMID 26317342, 2015). "Downregulation of MMP9 expression is associated with poor fetal growth and maternal preeclampsia most likely by a mechanism involving limited trophoblast invasion and poor transformation of maternal spiral arteries." (PMID 23696833, 2013). "Our previous studies demonstrated a higher level of KiSS-1 expression in association with a lower level of MMP-9 expression in the trophoblasts of women with preeclampsia compared with term pregnancy controls." (PMID 23145030, 2012). "Genetic polymorphisms in MMP-2 and MMP-9 transcription have been described in preeclampsia." (PMID 36835024, 2023). "The data demonstrating an association of MMP-9 in human preeclampsia are variable." (PMID 37089425, 2023). "Also, dysregulation of MMP-9 has been implicated in abnormal vasodilation, placentation, and uterine expansion in preeclampsia." (PMID 38107518, 2023). "On the other hand, this polymorphism, through elevation of MDA level and interaction with MMP9 −1562C>T polymorphism, might be associated with the risk of severe preeclampsia." (PMID 35885543, 2022). "In addition, MMP9 is crucial for trophoblast invasion, and aberrant expression of MMP9 in extravillous trophoblasts is linked to preeclampsia." (PMID 36457544, 2022). "Our study suggests that the MMP-9 -1562 C/T variant, associated with high MMP-9 production, could be a genetic risk factor for preeclampsia in Tunisian women." (PMID 34208487, 2021). "Gpr126-deficient placentas display down-regulation of preeclampsia markers Mmp9, Cts7, and Cts8." (PMID 34767447, 2021). "Moreover, deficiency of MMP9 results in impaired reproduction and phenocopies aspects of preeclampsia and IUGR in mice." (PMID 31424120, 2019). "Also, enzyme-linked immunosorbent (ELISA) assays revealed that plasma MMP-9 concentrations were increased in preeclampsia." (PMID 31703340, 2019).
preeclampsia (continued). "MMP-9 deficiency in pregnant mice simulated clinical features of preeclampsia and IUGR." (PMID 31671866, 2019). "To test this hypothesis, we deleted Pappa2 in a mouse model of preeclampsia and intrauterine growth restriction: deficiency of matrix metalloproteinase-9 (MMP9)." (PMID 29895300, 2018). "Our results also showed that the LGA births were associated with increased third trimester maternal plasma VEGF, decreased MMP-9 levels, positively associated with gestational hypertension, pre-pregnancy BMI, and parity (one previous birth) and negatively associated with maternal education." (PMID 30383759, 2018). "The present study examines whether the occurrence of single-nucleotide polymorphisms (SNP) in the MMP1, MMP2, MMP3, and MMP9 genes is related to the outcome of preeclampsia." (PMID 29670668, 2018). "Moreover, our study confirms the observations of other researchers that the promoter polymorphisms of the MMP2 and MMP9 genes exert an insignificant effect on preeclampsia development." (PMID 29670668, 2018). "The aim of the present study was to determine whether the most common MMP1, MMP2, MMP3, and MMP9 gene polymorphisms in maternal and fetal genes are associated with preeclampsia." (PMID 29670668, 2018). "Furthermore up-regulation of Kiss1 expression and down-regulation of MMP9 gene expression have been associated with pregnancies complicated by preeclampsia and IUGR." (PMID 23696833, 2013). "Additionally, vitamin C inhibits matrix metalloproteinase‐9 (MMP‐9) activity to maintain blood–brain barrier integrity and reduces pro‐inflammatory cytokine IL‐6 levels, alleviating neuroinflammation associated with gestational hypertension." (PMID 41476713, 2026). "This significantly higher concentration of PLAC1 protein could derive from an abnormal shedding of PLAC1 antigen, probably related to an aberrant function of proteolytic enzymes, MMP-2 and/or MMP-9, associated with preeclampsia as previously reported in literature." (PMID 36835024, 2023). "Downregulation of FLNB also contributes to decreased expression of ERK, MMP-2, and MMP-9, which in turn reduces placental trophoblast invasion in preeclampsia." (PMID 40638605, 2025). "While MMP-9 knockout mice have preexisting hypertension, the use of these mice as a comorbid model that develops preeclampsia-like symptoms requires consideration due to the uncharacteristic lack of elevated blood pressure during pregnancy." (PMID 37089425, 2023). "A recent meta-analysis showed that rs3918242 in matrix metalloproteinase 9 (MMP9) genes was associated with the susceptibility of HDP, especially preeclampsia and gestational hypertension." (PMID 35734434, 2022). "This study aimed to assess the potential role of MMP1, MMP9, TIMP1 and TIMP2 gene polymorphisms in the pathogenesis of preeclampsia." (PMID 35885543, 2022). "We investigated the association of MMP-9 polymorphism rs3918242 (-1562 C>T) and MMP-2 polymorphism rs2285053 (-735 C>T) with the risk of preeclampsia." (PMID 34208487, 2021). "Herein, omega‐3 supplementation decreased the protein level of MMP‐9 in brain tissues of adult pregnant female rats exposed to preeclampsia." (PMID 34174018, 2021). "An increased frequency of heterozygous MMP-9 -1562 C/T genotype carriers was observed in women with preeclampsia compared to healthy controls (p = 0.03)." (PMID 34208487, 2021). "There were lower MMP-9 levels and MMP-9/TIMP-1 ratios in gestational hypertension patients with the GG genotype for the TIMP-1 polymorphism than in those with the TT genotype." (PMID 33803206, 2021). "Data showed significant increase of MMP‐9 in PE rats compared to control pregnant rats and significant decreased in PE‐omega‐3 compared to preeclampsia pregnant rats." (PMID 34174018, 2021). "The object of the present study was to reveal the role of MMP-2 and MMP-9 in the development of severe preeclampsia." (PMID 33381317, 2020).
preeclampsia (continued). "In healthy pregnancies, some MMPs, for example, MMP8 and MMP9, are upregulated in uterine epithelial cells, and preeclampsia." (PMID 32296081, 2020). "A significant increase of MMP-9 concentrations in serum from women who subsequently developed preeclampsia can be detected during the first and third trimester of gestation." (PMID 28726716, 2017). "MMP-2 and MMP-9 have become of particular interest due to their frequent implications as key factors in the pathogenesis of preeclampsia." (PMID 28726716, 2017). "At delivery, urine concentrations of MMP-2 and MMP-9 were significantly elevated in women with severe preeclampsia compared to normal pregnancy, and this feature persisted 6 to 8 weeks after delivery." (PMID 28726716, 2017). "Early- and late-onset severe preeclampsia seem to be associated with increased maternal serum levels of MMP-2 and MMP-13 and decreased levels of MMP-9." (PMID 28798935, 2017). "Higher levels of MMP-2 and MMP-13 and lower levels of MMP-9 seem to be related to both early- and late-onset preeclampsia." (PMID 28798935, 2017). "Plasma concentration of MMP-2 and MMP-9 at 20 weeks of gestation was measured in women with suspected preeclampsia." (PMID 28726716, 2017). "Several studies show that MMP-9 increases along both, normal and preeclampsia-complicated pregnancy, while its inhibitor TIMP-1 increases in preeclamptic vs. normal pregnant women." (PMID 28726716, 2017). "A decrease in MMP-2 and MMP-9 interferes with the normal remodeling of spiral arteries at early pregnancy stages, leading to the initial pathophysiological changes observed in preeclampsia." (PMID 28726716, 2017). "In the case of MMP-9, it was reported that its circulating levels were correlated negatively with diastolic blood pressure among patients with gestational hypertension." (PMID 28143958, 2017). "Higher levels of MMP-2 and MMP-13 and lower levels of MMP-9 seem to be related to both early- and late-onset severe preeclampsia." (PMID 28798935, 2017). "We have previously reported that in trophoblasts from women with preeclampsia the expression levels of KiSS-1 were higher and those of MMP-9 were lower, as compared to normal controls." (PMID 23145030, 2012). "Increases in MMP-2 and MMP-9 in response to estrogen and progesterone promote placentation, uteroplacental vascularization and fetal growth during healthy pregnancy, but are altered in preeclampsia (PE)." (PMID 41897317, 2026). "While MMP-2 and MMP-9 are physiologically involved in trophoblast invasion and angiogenesis, and MMP-3 in cervical remodeling, their overexpression has been associated with pregnancy complications such as preeclampsia, infection, and preterm labor." (PMID 41450943, 2025). "Decreased vascular MMP9 expression may lead to reduced vasodilation, increased vasoconstriction, hypertensive disorders of pregnancy, and preeclampsia in humans." (PMID 41300775, 2025). "Interestingly, it has been shown that MMP9-KO mice have abnormal placenta and develop a preeclampsia phenotype." (PMID 35471950, 2022). "Decreased vascular MMP-2 and MMP-9 may lead to decreased vasodilation, increased vasoconstriction, hypertensive pregnancy, and preeclampsia." (PMID 35774422, 2022). "The MMP-9 activity in gestational hypertension was increased." (PMID 33803206, 2021). "MMP-9 knockout mice shows a phenotype mimicking preeclampsia." (PMID 33482846, 2021). "Of note, decreased vascular MMP-2 and MMP-9 may lead to decreased vasodilation, increased vasoconstriction, hypertensive disorders of pregnancy, and preeclampsia." (PMID 33803206, 2021). "The decrease in MMP-2 and MMP-9 activity or ratios of MMP-2/TIMP-2 and MMP-9/TIMP-1 might be involved in the pathogeneses of early pregnancy loss and preeclampsia." (PMID 33796532, 2021). "This study demonstrates that altered synthesis of MMP-9 in preeclampsia placentas may result from epigenetic changes of the methylation status of CpG sites in the promoter region." (PMID 33803206, 2021).
preeclampsia (continued). "Interestingly, other clinical trial showed that plasma MMP-9 concentrations are increased in women prior to presentation of preeclampsia." (PMID 31703340, 2019). "MMP2 and MMP9 are targeted by many miRNAs, which may contribute to the pathogenesis of preeclampsia and IUGR." (PMID 31671866, 2019). "Moreover, few clinical studies have evaluated the role of MMP-2 and MMP-9 in the pathophysiology of preeclampsia." (PMID 31703340, 2019). "While the publication describing Mmp9 deletion as a model of preeclampsia and intrauterine growth restriction reported “as much as a 50% reduction in litter size”, no data were presented, and the original report of Mmp9 deletion described a much more modest reduction in litter size (1.6 pups)." (PMID 29895300, 2018). "A decrease in the level of MMP9 expression might inhibit the invasion of EVT cells, and thus cause preeclampsia." (PMID 30478366, 2018). "The levels of MMP-9 were lower in the patients with pregnancy complicated by severe preeclampsia." (PMID 28798935, 2017). "Maternal serum levels of MMP-9 were lower in patients with pregnancies complicated by preeclampsia." (PMID 28798935, 2017). "Increased MMP-2 and MMP-9 methylation is observed in villous samples of preeclamptic patients; this gene silencing explains the low concentrations of these enzymes and supports the trophoblast invasion defects seen in preeclampsia." (PMID 28726716, 2017). "A dysregulated secretion of these enzymes could interfere the physiological trophoblast invasion, i.e., the trophoblast in preeclampsia will produce less MMP-9 and MMP-9 inhibition or gene silencing, affecting trophoblast invasion in vitro." (PMID 28726716, 2017). "Currently, due to its role in angiogenesis, invasiveness, metastasis, and ECM reorganization, the suitability of MMP-9 as a biomarker is also extensively investigated in different types of cancers, cardiovascular diseases, and pregnancy complications such as preeclampsia." (PMID 39337591, 2024). "They report an association of the MMP9 SNP with gestational hypertension, but not with PE." (PMID 30618791, 2018). "We predicted that, if the elevated expression of PAPP-A2 in preeclampsia in humans reflects a compensatory response, then deletion of Pappa2 in mice would exacerbate effects of Mmp9 deletion, i.e., mice null for both Pappa2 and Mmp9 would show a more severe phenotype than mice null for Mmp9 only." (PMID 29895300, 2018). "In view of the literature data, the results of the present study may suggest the importance of lower maternal serum MMP-9 levels in abnormal development of blood vessels at the interface between mother and fetus in pregnancies complicated by severe preeclampsia." (PMID 28798935, 2017). "Indeed, a number of genes regulated in this array were previously found to be associated with pregnancy complications such as preeclampsia (MR, CCL2, IGF-1, secreted phosphoprotein (SPP)-1, MMP-9), preterm labour (CCL18) and intrauterine growth restriction (IGF-1)." (PMID 18446208, 2008). "The abnormal production of matrix metalloproteinases (MMPs), especially MMP-9 and MMP-2, plays a pivotal role in hypertensive disorders of pregnancy, and as such, can influence the development of preeclampsia." (PMID 34208487, 2021). "In a different study, 14 biomarkers for preeclampsia, including MMP-2 and MMP-9, were evaluated in urine samples." (PMID 28726716, 2017). "Even though most evidence links increased circulating levels of MMP-9 and -2 with preeclampsia, two interesting reports show that pro-MMP-9, MMP-9 and MMP-9/TIMP-1 ratio remain unchanged in preeclamptic pregnancies in the Brazilian population." (PMID 28726716, 2017). "The aim of this study was to evaluate the predictive value of maternal inflammatory status, assessed through biomarkers of inflammation (CRP, chorioamnionitis, preeclampsia), and neonatal inflammatory markers (CRP 1, CRP 2, PCT, IL3, MMP9) on the incidence of NEC in preterm neonates." (PMID 40295408, 2025).